HDAC1 (histone deacetylase 1)
Diseases named in the same sentence as HDAC1 in open-access papers (continued):
Sharing a sentence is not in itself a finding about the gene and the disease.
colorectal cancer (continued). "In colorectal cancer patients HDAC1, 2, and 3 are overexpressed, and high HDAC1 and 2 expression is linked with reduced patient survival." (PMID 24808866, 2014). "In addition, sulforaphane is an HDAC inhibitor used to treat colorectal cancer that can inhibit tumor progression by targeting HDAC1 and HDAC2." (PMID 41513612, 2026). "For example, the CBP/p300 inhibitor CPI-0610 shows promise in preclinical models of pancreatic cancer by disrupting the lactylation-TTK/BUB1B feedback loop, while HDAC1 agonist entinostat reverses immunosuppression in colorectal cancer by de-repressing CD8+ T cell infiltration." (PMID 40755753, 2025). "Evidence has shown that in colorectal cancer models, dual inhibition therapy targeting DNA methyltransferase and histone deacetylase (C02S, targeting HDAC1, 2, 3, 8) not only upregulates tumor ERV expression but also activates viral mimicry responses through the MDA5–MAVS signaling pathway." (PMID 40573881, 2025). "SOX4 overexpression promotes sphere formation and the self-renewal of colorectal cancer cells, which directly bind to the HDAC1 promoter, encouraging HDAC1 transcription and thereby stem cell maintenance, Wnt, Notch, the cell cycle, and transcriptional misregulation pathways in cancer." (PMID 39228892, 2024). "From a cancer therapeutics perspective, the substantial tumor growth inhibition observed in our xenografts provides a strong rationale to combine Bcl-xL blockade, using navitoclax or HDAC1–3 inhibition with KRASG12C inhibitors in patients with colorectal cancer." (PMID 36279564, 2023). "In addition, inhibitors of HDAC1 have been developed and placed in more well-established pre-clinical and clinical systems to treat cancers, including colorectal cancer, hepatocellular carcinoma, and neuroblastoma." (PMID 37760477, 2023). "Histone deacetylase 1 (HDAC1) regulates CIP2A/p90 gene expression in colorectal cancer cells." (PMID 36911405, 2023). "Several class I HDACs—HDAC1, 2, 3—and eight isotypes have been involved in colorectal cancer." (PMID 35008525, 2021). "Thus, decreased miR-34a expression contributes to a miR-449a-mediated negative feedback loop to maintain low levels of miR-449a/34a and high levels of SATB2, Sirt1, HDAC1 and DNMT3a in colorectal cancer cells." (PMID 29254139, 2017). "Sub-group analyses showed that the expression level of HDAC1 in the low-differentiated cancer patients was higher than that in the moderate/high-differentiated cancer patients with colorectal cancer (OR = 3.80, 95% CI = 1.46–9.92) and liver cancer (OR = 2.50, 95% CI = 1.45–4.30)." (PMID 28424407, 2017). "However, the OS rate was comparable between patients with low HDAC1 expression and those with high HDAC1 expression in colorectal cancer (HR = 0.87, 95% CI = 0.66–1.13, P = 0.30), liver cancer (HR = 1.71, 95% CI = 0.76–3.86, P = 0.19) and pancreatic cancer (HR = 1.43, 95% CI = 0.71–2.88, P = 0.32)." (PMID 28424407, 2017). "Beyond ovarian and colorectal cancers, CBP/p300 and HDAC1–3 exhibit context-dependent roles in multiple malignancies." (PMID 40755753, 2025). "We also demonstrated that MPT0G236 inhibited the activity of Class I HDACs (HDAC1, HDAC2, HDAC3, and HDAC8), as well as of a Class IIb HDAC, HDAC6, leading to the increased acetylation of α-tubulin and histone H3 in both colorectal cancer cells." (PMID 37628767, 2023). "The inhibition of HDAC1 by (S)-2 downregulated the transcription of CIP2A/p90 and unleashed PP2A activity, thereby inducing growth arrest and apoptosis in colorectal cancer cells." (PMID 36911405, 2023). "In colorectal cancer, emerging evidence has shown that PPARG signaling is downregulated due to the regulatory actions of EZH2 and HDAC1." (PMID 36142846, 2022). "HDAC-1 overexpression has been correlated with poor survival in mobile tongue SCC, gastric and colorectal carcinoma, intrahepatic cholangiocarcinoma and urothelial bladder endometrial and ovarian carcinoma, especially of endometrioid type." (PMID 33799478, 2021).
colorectal cancer (continued). "Class-I HDACs consisting of HDAC1, HDAC2, HDAC3 and HDAC8, are well known oncogenic proteins expressed at high levels in malignant cervical and colorectal cancers." (PMID 29190639, 2017). "Additional evidence also supported that HDAC1, HDAC2 and HDAC6 over-expression were observed in the stage III colorectal cancer tissues when compared with normal tissues." (PMID 26087180, 2015). "HDAC1, HDAC5, HDAC7A, SIRT1, and SUV39H1 expression profiles were distinctive for colorectal cancers and normal colorectal mucosa." (PMID 16638127, 2006). "Pulldowns using a lysate of the colorectal cancer cell line SW620 showed clear dose-dependent competition of HDAC1, HDAC2 (including co-competed members of the HDAC1/2 containing CoREST complex), and HDAC6 for both (R/S)-LA and (R/S)-LM with affinities in the range of 3–33 μM." (PMID 37322067, 2023). "Laccaic acid could produce epigenetic modifications in colorectal cancer, primarily downregulating DNMT1 and HDAC1 expression." (PMID 34835969, 2021). "On the contrary, heterogeneous HDAC-1 expression (high and low) has been correlated with lymph node metastasis in colorectal cancer." (PMID 33799478, 2021). "In this study, by identification of SOX4-induced proteome changes in colorectal cancer stem cells (CRC-SCs), we investigated the potential molecular effects of SOX4 in CRC-SCs and found that SOX4 transcriptionally regulates HDAC1 to support the stemness of CSCs." (PMID 33482915, 2021). "In addition, the combinatorial treatment of PEITC with laccaic acid (LA) showed synergistic antitumor activity on colorectal cancer cells with noticeable ability to down-regulate the expression of DNMT1 and HDAC1." (PMID 34835969, 2021). "This process requires a novel LncRNA, ENSG00000274093.1, which binds to HDAC2 and may act as a modular scaffold for the HDAC1/HDAC2 and EZH2 complexes, thereby altering EMT in colorectal cancer cells." (PMID 33325150, 2021). "Statistical analysis of the data indicated that there was a negative correlation between B7x and HDAC1 levels in tumor tissue from colorectal cancer patients (P < 0.01)." (PMID 32934224, 2020). "In contrast, the expression of HDAC1 was not related to the overall survival of the colorectal cancer patients (P = 0.35, left)." (PMID 32934224, 2020). "Together, these results suggest that the expression level of HDAC1 in gastrointestinal malignancies, especially in colorectal cancer, is higher than that in noncancerous tissues." (PMID 28424407, 2017). "The meta-analysis results suggested that the expression of HDAC1 in gastrointestinal cancer tissues, especially colorectal cancer tissue, is higher than that in noncancerous tissues." (PMID 28424407, 2017). "In our study we did not observe significant expression changes of HDAC1 when comparing tumour and normal tissue samples, except for colorectal cancers." (PMID 16638127, 2006). "Thus, our study has identified a novel LncRNA, ENSG00000274093.1, which bound HDAC2, HDAC1 and EZH2, and may act as a modular scaffold of HDAC1/HDAC2 and EZH2 Complexes, and consequently altered EMT of the colorectal cancer cell." (PMID 33325150, 2021).
glioma (52 papers, 2013 to 2026). A benign or malignant brain and spinal cord tumor that arises from glial cells (astrocytes, oligodendrocytes, ependymal cells). "High HDAC1 expression was significantly associated with the clinical stage of glioma and reduced OS." (PMID 40867242, 2025). "HDAC1 overexpression in gliomas is significantly associated with higher tumor grade, poorer prognosis, and increased immune infiltration, and is a key component of the prognostic signature." (PMID 38801243, 2024). "Bioinformatics analysis in this study indicated that high expression of HDAC1 in glioma was associated with the extracellular matrix (ECM) and poor prognosis." (PMID 39595109, 2024). "HDAC1 is also highly expressed in glioma tissue, and high expression of glioma is associated with glioma cell proliferation, migration, invasion, angiogenesis, and a poor prognosis." (PMID 35545840, 2022). "We also found that the expression of HDAC1 was elevated in glioma tissues and was associated with a poor prognosis." (PMID 35545840, 2022). "Since HDAC1 was filtered out to be the prognostic gene for glioma, the association between the immune infiltration and the HDAC1 expression was analyzed by the TIMER database." (PMID 34540896, 2021). "According to the log-rank test and Kaplan-Meier analysis, higher HDAC1 expression associated with a poor prognosis of patients with glioma." (PMID 28624794, 2017). "Samples with low HDAC1 expression were associated with more neuronal features and better prognosis, indicating that inhibiting HDAC1 may be associated with the neuronal-like differentiation of glioma cells induced by parthenolide." (PMID 39595109, 2024). "The inhibition of HDAC1 expression in glioma cells may potentially be associated with these effects, although further investigation is needed to confirm the underlying mechanism." (PMID 39595109, 2024). "We also found elevated HDAC1 expression in glioma tissues, which is associated with poor prognosis." (PMID 36227941, 2022). "The GEPIA database showed that HDAC1/2/3/4/5/7/9/10/11 mRNA expression levels were significantly associated with glioma patient prognosis and could, therefore, be exploited as biomarkers for the prediction of glioma patient survival." (PMID 35359455, 2022). "The HDAC1-related signature was adjusted as an independent risk indicator and eventually validated both internally and externally showing reliable discrimination for glioma prognosis prediction." (PMID 34540896, 2021). "As a result of high expression of HDAC1 was associated with poor prognosis of patients with glioma, we suspected that HDAC1 might act as a potent oncogene in glioma." (PMID 28624794, 2017). "Thus, the increased expression of HDAC1 may be associated with the abnormal cellular proliferation and invasiveness potential of gliomas." (PMID 28624794, 2017). "Mechanistically, PAX3 expression positively correlated with HDAC1/2/3 levels, and its knockdown increased glioma cell sensitivity to vorinostat." (PMID 41180518, 2025). "In gliomas, targeting HDAC1 and HDAC2 has been shown to potentially inhibit tumor progression and enhance glioblastoma cell sensitivity to treatment." (PMID 41331688, 2025). "Based on the RNA-seq results of U251 cells and glioma clinical data, we evaluated the expression levels of class I HDACs (HDAC1, 2, 3) and class IIb HDACs (HDAC6) in U251 cells treated with sodium butyrate." (PMID 40297576, 2025). "This was further supported by a study conducted on glioma tissues, where a direct correlation was observed between HDAC1 levels and cancer progression." (PMID 40581884, 2025).
glioma (continued). "While no obvious HDAC candidate has yet emerged based on preferential baseline expression in IDHmut gliomas, others have shown that IDHmut gliomas are especially reliant on HDAC1 and HDAC6 activity." (PMID 41066183, 2025). "In glioma cells, strong nuclear expression of HDAC1, HDAC2, and NCOR2 has been observed, while NCOR1 and HDAC3 show weaker expression." (PMID 40940748, 2025). "Differences in gene expression between glioma samples with high and low HDAC1 expression were analyzed via the CGGA database." (PMID 39595109, 2024). "Bioinformatics analysis based on the CGGA database was conducted to evaluate the role of HDAC1 in glioma." (PMID 39595109, 2024). "HDAC1 can be a viable treatment target for gliomas as it has been demonstrated to influence cell invasion, proliferation, and apoptosis." (PMID 38801243, 2024). "For example, HDAC1, 2, 3, and 7 have been found to be overexpressed in grade IV gliomas compared to normal brain tissue and low-grade gliomas." (PMID 38183103, 2024). "Recent studies on HDAC1 in glioma have shown that HDAC1 is a necessary class I HDAC in GSCs that maintains the malignant phenotype of GSCs and promotes the progression of GBM." (PMID 39595109, 2024). "Our analysis results showed that BRCA1 and HDAC1 were highly expressed in gliomas, while the expression results of RANGAP1 were opposite." (PMID 38801243, 2024). "Consistent with our results, high expression of HDAC1, CASP3, REST, GNAI3, FZD1, EPHB4 was found to correlate with poor prognosis of glioma, and inhibitors of HDAC1 inhibited the EMT process in glioma cells thereby affecting cell migration and invasion." (PMID 38629068, 2024). "Of the eleven annotated HDAC enzymes (HDAC1-11) only six are expressed in IDH1 mutant glioma tissue samples and patient-derived gliomasphere lines (HDAC1-4, HDAC6, and HDAC9)." (PMID 37528157, 2023). "Among the HDAC1-related signatures for precise prognosis prediction in glioma, HDAC1 indicates prognosis and immune infiltration." (PMID 37370767, 2023). "Univariate Cox regression indicated that high expression levels of HDAC1, HDAC3, HDAC7 and HDAC9 were associated with poor OS of glioma, and elevated expression levels of HDAC4, HDAC5, HDAC6 and HDAC11 were associated with a favorable prognosis of glioma." (PMID 35545840, 2022). "HDAC1 is also highly expressed in glioma tissues, and high expression of glioma is related to the proliferation, migration, invasion, angiogenesis, and poor prognosis of glioma cells." (PMID 36227941, 2022). "HDAC1 knockdown has been consistently proven to decrease the expression of Snail in glioma cells thus suppressing cancer progression." (PMID 35395834, 2022). "Our results showed that HDAC1 was highly expressed in glioma tumor tissue and significantly correlated with patient survival and immune infiltrate density." (PMID 35359455, 2022). "The glioma cells show on average 90% higher HDAC1, 108% higher HDAC2 and 23% higher HDAC3 protein expression than astrocytes." (PMID 35365623, 2022). "First, we demonstrated that HDAC1/3/8 are overexpressed in glioblastoma tissue compared to normal brain tissue and that HDAC1/2/3 are overexpressed in glioma and glioma initiating cell lines." (PMID 35365623, 2022). "We searched the cell atlas of the HDAC family in glioma and observed immunofluorescence of HDAC1/2/3/4/5/7/9." (PMID 35359455, 2022). "We plan to knock out or use the expression of protease inhibitor HDAC1 in glioma cell lines to observe tumor cell invasion and migration in functional experiments." (PMID 35359455, 2022). "Low and medium HDAC1/4/8/9/10 protein expression levels were determined for normal tissues, and high HDAC1/4/8/9/10 protein expression levels were found in glioma tissues." (PMID 35359455, 2022).
glioma (continued). "In contrast to less efficient discrimination of HDAC2 and HDAC11, the AUC value of HDAC1 over 0.7 throughout the time points manifested that HDAC1 was identified to be a promising prognostic biomarker for glioma." (PMID 34540896, 2021). "HDAC1 was both a prognostic and immune infiltration indicator and a central component of the HDAC1-related signature for precise prognosis prediction in glioma." (PMID 34540896, 2021). "HDAC1 was manifested to serve as a prognostic biomarker for glioma, and an indicator for neutrophil and CD4+ T cell infiltration in LGG." (PMID 34540896, 2021). "It exposed the pivotal role of HDAC1 in glioma, as both an independent prognostic and immune infiltration biomarker and a central component of the HDAC1-related signature for precise prognosis prediction." (PMID 34540896, 2021). "Ultimately, the HDAC1-centered signature composed of the HDAC1-related genes was developed and validated for precise prognosis prediction in glioma." (PMID 34540896, 2021). "We compared HDAC1 and HDAC2 protein expression in gliomas using the Human Proteome Atlas and found that both were strongly expressed in most gliomas, although HDAC1 expression is higher in GBM than in low-grade gliomas." (PMID 34494550, 2021). "The expression profiles of the HDAC1-related signature components were investigated in the TCGA glioma cohort." (PMID 34540896, 2021). "Among these LARs that showed increased expression with increasing WHO grade in both the CGGA and TCGA datasets, HDAC1 is the best-studied LAR in glioma, whereas the potential functions of ESCO2, KAT1, LEF1, and SLC16A10 are unreported in this cancer." (PMID 33718432, 2021). "The prognostic value of HDAC1 was validated with ROC achieving 0.70, 0.77, 0.75, and 0.80 as separability for 1-, 3-, 5-, and 10-years OS predictions in glioma, respectively." (PMID 34540896, 2021). "The separability of the HDAC1 turned out to be valid, reaching 0.70, 0.77, 0.75, and 0.80 for 1-, 3,- 5-, and 10-years OS predictions in glioma, respectively." (PMID 34540896, 2021). "Knockdown of HDAC1 resulted in a significant decrease in the expression of glioma master transcription factors SOX2 and OLIG2, stem cell marker NESTIN, and the receptor tyrosine kinase epidermal growth factor receptor (EGFR)." (PMID 34494550, 2021). "High expression of HDAC1 increases invasion and proliferation of glioma cells which promotes the progression and recurrence of glioma tumors." (PMID 32903420, 2020). "A total of 18 genes were significantly negatively correlated with DGCR5, including GNAI3, VIM, ITGB1, HIF1A, and HDAC1, all of which are critical factors affecting glioma development." (PMID 33085646, 2020). "Knockdown of HDAC1 can inhibit cell proliferation, inhibit invasion of glioma cell lines, and induce cell apoptosis." (PMID 28624794, 2017). "Then, we analyzed the expression levels of HDAC1 in 105 snap-frozen glioma tissues and 25 normal brain tissues using RT-PCR and Western blot assays." (PMID 28624794, 2017). "Mechanistic basis for the pathological and clinical observations in this study was further validated by assessing the biological functions of HDAC1 on glioma cell proliferation, apoptosis, migration and invasion." (PMID 28624794, 2017). "Significant nuclear expression of HDAC1 has been found in glioma cells during tumor recurrence and malignant tumor progression." (PMID 28624794, 2017). "Downregulation of HDAC1 inhibited cell proliferation, prevented invasion of glioma cell lines, and induced cell apoptosis." (PMID 28624794, 2017). "HDAC1 expression was closely related with pathological grade and overall survival of patients with gliomas." (PMID 28624794, 2017).